CCL23 (C-C motif chemokine ligand 23)
Diseases named in the same sentence as CCL23 in open-access papers (continued):
Sharing a sentence is not in itself a finding about the gene and the disease.
rheumatoid arthritis (6 papers, 2013 to 2025). A chronic, systemic autoimmune disorder characterized by inflammation in the synovial membranes and articular surfaces. "CCL23-dependent signaling has been implicated in several inflammatory disease states including rheumatoid arthritis and IBD." (PMID 37170273, 2023). "The expression of CCL-23 mRNA was found in monocytes stimulated with IL-1β and IL-4 and can also be detected in SFs from patients with rheumatoid arthritis." (PMID 40083631, 2025).
hepatocellular carcinoma (5 papers, 2021 to 2025). A malignant tumor that arises from hepatocytes. "Chemokine (C-C motif) ligand 23 (CCl23) has been associated with tumor progression in hepatocellular carcinoma (HCC), but its role in the context of BTC is largely unknown." (PMID 36505756, 2022). "Moreover, approaches to reactivate CCL23 combined with immune checkpoint blockade or chemotherapy drugs may provide novel opportunities to target hepatocellular carcinoma." (PMID 34671553, 2021).
ischemic stroke (5 papers, 2022 to 2025). A stroke disorder caused by obstruction of blood flow to the brain, due to thrombotic (local blood clot formation) or embolic (due to a blood clot or other material traveling from another site) event. "Not uniquely, some research groups have considered CCL23 as a novel CC chemokine involved in human brain injury and a promising biomarker of injury in ischemic stroke patients." (PMID 40133606, 2025).
melanoma (4 papers, 2021 to 2024). A malignant, usually aggressive tumor composed of atypical, neoplastic melanocytes. "Based on our previous experience with IFN‐γ in melanoma model, we performed proliferation assay on CCL23 and UM‐SCC1 cells by treating them with IFNs with and without APG‐157." (PMID 38686626, 2024). "Regarding chemokines, CCL1, CCL17, CCL22 and CCL23, were significantly increased in FGFR Mut melanoma (all P < 0.05)." (PMID 36426352, 2022).
mild cognitive impairment (4 papers, 2021 to 2025). "CCL23, a chemokine implicated in inflammation and host defence responses, has been frequently reported as a potential blood biomarker for mild cognitive impairment to AD progression." (PMID 40133606, 2025). "In AD, both CCL23 levels in the CSF as well as APOE4 status are known as independent predictors for conversion from mild cognitive impairment (MCI) to dementia." (PMID 37834363, 2023).
atherosclerosis (3 papers, 2020 to 2025). A disease characterized by the build-up of fatty material and calcium deposition in the arterial wall resulting in partial or complete occlusion of the arterial lumen. "Substantial evidence indicates that the blood level of CCL23 can reflect the progression of several inflammatory diseases, including atherosclerosis, systemic mastocytosis, systemic sclerosis, acute myeloid leukemia, and chronic kidney disease." (PMID 38045696, 2023).
autoimmune disease (3 papers, 2022 to 2025). A disorder resulting from loss of function or tissue destruction of an organ or multiple organs, arising from humoral or cellular immune responses of the individual to their own tissue constituents. "Chemokines such as CCL17, CCL23, and CXCL9 are frequently upregulated in autoimmune diseases." (PMID 40564127, 2025).
biliary tract cancer (3 papers, 2022 to 2024). "In biliary tract cancers, elevated serum CCL23 predicted a dismal prognosis, and PEA-measured high plasma CCL28 levels implied worse survival in epithelial ovarian cancers." (PMID 38594742, 2024).
dementia (3 papers, 2021 to 2023). Loss of intellectual abilities interfering with an individual's social and occupational functions. "Since it has recently been demonstrated that the presence of one or more APOE4 alleles in PD is associated with higher odds of developing dementia, as well as a shorter time to develop dementia, we investigated the relationship between CCL23 levels and APOE4 genotype." (PMID 37834363, 2023).
systemic sclerosis (3 papers, 2022 to 2024). A chronic disorder, possibly autoimmune, marked by excessive production of collagen which results in hardening and thickening of body tissues. "CCL23 has been reported to be associated with brain injury, immune response, systemic sclerosis, rhinosinusitis and other diseases." (PMID 35001801, 2022).
acute myeloid leukemia (2 papers, 2023). Acute myeloid leukemia (AML) is a group of neoplasms arising from precursor cells committed to the myeloid cell-line differentiation. "Another study on patients with acute myeloid leukemia (AML) showed a relationship between high levels of CCL23 and a higher percentage of leukemic cells in peripheral blood." (PMID 37185750, 2023).
Arthritis (2 papers, 2019 to 2025). Inflammation of a joint. "Serum CCL23 has been described as a RA activity biomarker; however, murine CCL6 has not been ascribed a role in murine arthritis models." (PMID 30937315, 2019).
asthma (2 papers, 2021 to 2023). "Here, increased C-C chemokine ligand 6 (CCL6) in asthmatic mice and the human orthologs CCL15 and CCL23 that are highly expressed in asthma patients are described, which are mainly derived from eosinophils." (PMID 33640900, 2021).
chronic kidney disease (2 papers, 2022 to 2023). Impairment of the renal function secondary to chronic kidney damage persisting for three or more months. "Serum CCL23 has been implicated in multiple inflammatory diseases, such as systemic sclerosis, chronic rhinosinusitis, chronic kidney disease, and atherosclerotic disease." (PMID 36498453, 2022).
glioma (2 papers, 2021 to 2022). A benign or malignant brain and spinal cord tumor that arises from glial cells (astrocytes, oligodendrocytes, ependymal cells). "We found that the following neutrophil chemokines—MMP9, CCL2, CCL5, CXCR4, CXCR2, CCL23, and IL8 (p = 0.07)—were enriched in TERTmut gliomas (t-test, p < 0.05)." (PMID 33996815, 2021).
Hepatic steatosis (2 papers, 2020 to 2021). Steatosis is a term used to denote lipid accumulation within hepatocytes. "The plasma level of CCL23 has also been associated with plasma oxidative low‐density lipoprotein, which could affect the redox balance in hepatic cells, and the latter has been linked to hepatic steatosis in recent studies." (PMID 32337855, 2020). "The plasma levels of CCL23 and CD8A have also been associated with hepatic steatosis." (PMID 34694070, 2021).
hypoglycaemia (2 papers, 2023 to 2024). "BMI correlated inversely with changes of PD-L1 and CD40 during hyperinsulinemia, Oncostatin-M, TNFSF14, FGF-21 and 4EBP-1 during hypoglycemia and CCL23, VEGF-A and CDCP1 during hyperglycemia (Rho ≤ -0.50)." (PMID 37400734, 2023). "In addition, CXCL9, CCL23, CCL3 and CLL4 increased in response to hypoglycaemia, which can recruit immune cells, thus potentially contributing to the persistently elevated levels of circulating white blood cells." (PMID 38331900, 2024).
injury (2 papers, 2022). Damage inflicted on the body as the direct or indirect result of an external force, with or without disruption of structural continuity. "After brain injury, CCL-23 and CXCL-12 modulate immune response through promoting migration of monocytes to the local sites of injury." (PMID 36315566, 2022). "Secondly, CCL23 concentrations in cerebrospinal fluid (CSF) are remarkably higher than those in peripheral blood, suggesting that CSF CCL23 concentrations might better reflect the inflammation of brain injury." (PMID 36498453, 2022).
nasal polyps (2 papers, 2018 to 2022). "Poposki and colleagues were able to show strong production of CCL23 in nasal polyps, which was largely colocalized with ECP, indicating predominantly eosinophilic CCL23 production in nasal polyps." (PMID 29564208, 2018). "In addition, significantly increased CCL23 expression is seen in nasal polyps in patients with N‐ERD." (PMID 29564208, 2018). "CCL23 is a chemoattractant for monocytes, dendritic cells, and lymphocytes, and it has been shown that CCL23 induces endothelial cell migration via the CC motif chemokine receptor CCR1, which is also upregulated in nasal polyps." (PMID 29564208, 2018).
pancreatic carcinoma (2 papers, 2023). "Of the five most used proteins in the BTC signatures (IL-6, IL-15, PTN, CCL23, and MUC-16), only IL-6 was used in the primary pancreatic cancer signatures." (PMID 36831406, 2023).
Sepsis (2 papers, 2022 to 2024). Sepsis is defined as life-threatening organ dysfunction caused by a dysregulated host response to infection. "Among the ICU Day-1 classifying proteins IL-10, CCL23, and TGFα1, significantly decreased in sepsis patient plasma by Day-3." (PMID 36572854, 2022). "CCL23 is a chemokine that is highly chemotactic for T-cells and monocytes, and has reported age-related differences in sepsis." (PMID 36572854, 2022). "Infants who developed sepsis had higher levels of the proteins CCL20, CCL23 and CCL25 in infant plasma week 4 compared to infants who did not." (PMID 38001236, 2024). "The association between higher AF and lower levels of CCL20, CCL23 and CCL25 in infant plasma, and lower plasma levels in infants who did not develop sepsis support our hypothesis that AF may have protective properties." (PMID 38001236, 2024).
acute GVHD (1 paper, 2024). "Early detection of serum levels of CCL23 and CXCL9 in patients undergoing HSCT can effectively predict the risk of developing acute GVHD." (PMID 39840040, 2024).
adenoma (1 paper, 2011). A neoplasm arising from the epithelium. "CCL19, CCL21, CCL23, CCL5, were found to have reduced expression in the adenoma and adenocarcinoma compared to normal mucosa." (PMID 21249124, 2011).
bacterial meningitis (1 paper, 2019). Inflammation of the membranes surrounding the brain and spinal cord due to a bacterial infection. "When comparing cytokine levels between viral and bacterial meningitis, CCL23 and CXCL6 showed the biggest differences between both diseases but differences did not remain significant when applying Bonferroni’s correction." (PMID 31727097, 2019).
Cerebral ischemia (1 paper, 2022). Restriction of arterial blood supply to the brain associated with insufficient oxygenation to support the metabolic requirements of the tissue. "Notably, CCL23 is also involved in the inflammatory response of brain injury and serves as a prognostic biomarker of Alzheimer’s disease and cerebral ischemia." (PMID 36498453, 2022).
cognitive decline (1 paper, 2023). "Increased CCL23 levels were associated with cognitive decline and the APOE4 genotype." (PMID 37834363, 2023).
endometriosis (1 paper, 2023). The growth of functional endometrial tissue in anatomic sites outside the uterine body. "Two markers (EN-RAGE and CCL23) known for their chemoattractant characteristics were found to be increased in plasma of endometriosis patients compared to controls." (PMID 36902452, 2023). "CCL23 has never, to our knowledge, been associated with endometriosis in previous studies." (PMID 36902452, 2023).
experimental autoimmune encephalomyelitis (1 paper, 2019). An autoimmune demyelinating disease of the central nervous system that is produced experimentally in animals by the injection of homogenized brain or spinal cord in Freund's adjuvant. "For example, it is expressed in neurons or infiltrating blood cells after ischemia in rats, or microglia/macrophages in a mouse model of experimental autoimmune encephalomyelitis; moreover, CCL23 is expressed in infiltrating blood cells of the infarcted human brain." (PMID 31362699, 2019).
fibromyalgia (1 paper, 2022). A chronic disorder of unknown etiology characterized by pain, stiffness, and tenderness in the muscles of neck, shoulders, back, hips, arms, and legs. "The top five proteins that distinguished fibromyalgia patients from plasma controls were in serum STAMBP, SIRT2, CD40, AXIN1 and IL-7 and in CSF (CCL19, CCL23, IL-18, CX3CL1, FGF19, CXCL10, CCL11)." (PMID 36327322, 2022).
gout (1 paper, 2023). A condition characterized by painful swelling of the joints, which is caused by deposition of urate crystals. "Six significantly distinct proteins were identified in the serum proteomic profile of gout flares, these patients having elevated circulating concentrations of MMP-1, IL-6, VEGFA, and CCL23 and decreased DNER (Delta and Notch-like epidermal growth factor-related receptor) and CD6 levels." (PMID 37810213, 2023).
Granuloma (1 paper, 2025). A compact, organized collection of mature mononuclear phagocytes, which may be but is not necessarily accompanied by accessory features such as necrosis. "In contrast, reduced levels of MPIF-1/CCL23 in progressors suggest a disruption in granuloma formation, which facilitates disease progression—this finding diverges from previous studies." (PMID 40959138, 2025).
gynecologic cancers (1 paper, 2025). "Future experiments are needed to examine the phosphorylation status of STAT3 and to understand the cell signaling pathways, which are activated by CCL23 in ovarian and other gynecologic cancers." (PMID 41463176, 2025).
insomnia (1 paper, 2023). A sleep disorder characterized by difficulty in falling asleep and/or remaining asleep. "Higher levels of CCL23, CD4, Gal-1 and MMP7 at baseline were all strongly associated with insomnia at EOT." (PMID 37936126, 2023). "In this study, high levels of four inflammatory proteins; CCL23, CD4, Gal-1, and MMP7, at baseline correlated strongly with insomnia at EOT." (PMID 37936126, 2023).
Kawasaki disease (1 paper, 2026). A rare inflammatory disease characterized by an acute febrile, systemic, self-limiting, medium-vessel vasculitis primarily affecting children. "Further receiver operating characteristic (ROC) analysis showed that CCL23 exhibited good sensitivity and specificity in distinguishing Kawasaki Disease from other diseases." (PMID 41789072, 2026).
lung diseases (1 paper, 2023). "Murine CCL6 shares homology with human CCL23/CCL15, which perform the similar roles in lung diseases." (PMID 36934284, 2023).
lymphadenitis (1 paper, 2023). Acute or chronic inflammation of one or more lymph nodes. "CXCL9/MIG, CCL20, CCL23, CXCL10/IP-10, CXCL1, CXCL2, and CXCL8 significantly declined in our cohort of EPTB (48 TB pleuritis and 57 TB lymphadenitis) patients at both time points." (PMID 36635313, 2023).
osteoarthritis (1 paper, 2024). A noninflammatory degenerative joint disease occurring chiefly in older persons, characterized by degeneration of the articular cartilage, hypertrophy of bone at the margins and changes in the synovial membrane. "Although circulating inflammatory proteins may not mediate the occurrence of osteoarthritis resulting from skeletal muscle loss, this study found that high levels of CCL23, LAP-TGF-β1, and LIFR might contribute to reduce the risk of KOA, while high levels of FGF19 might increase the risk of KOA." (PMID 38811889, 2024).
ovarian tumors (1 paper, 2025). "CCL23 is a potent chemoattractant for myeloid cells that stimulates chemotactic migration of endothelial cells to support tumor angiogenesis in ovarian tumors and increases the proportion of exhausted CD8+ T-cells in the TME." (PMID 41463176, 2025).
periodontitis (1 paper, 2021). An acute or chronic inflammatory process that affects the tissues that surround and support the teeth. "On the contrary, when considering radiographic bone loss, only CCL23 remained significantly associated with periodontitis after adjustment." (PMID 34385358, 2021). "However, after adjustment for age and smoking, two factors that have a strong influence on the severity of periodontitis, only one protein, CCL23, remained associated with periodontitis." (PMID 34385358, 2021).
primary sclerosing cholangitis (1 paper, 2022). "Interestingly, BTC patients also showed significantly higher CCL23 levels compared to patients with primary sclerosing cholangitis (PSC, p = 0.033)." (PMID 36505756, 2022). "CCl23 serum levels were analyzed by multiplex immunoassay in a cohort of 119 BTC patients receiving surgical tumor resection as well as 50 healthy control samples and 11 patients with primary sclerosing cholangitis (PSC)." (PMID 36505756, 2022).
prostate carcinoma (1 paper, 2023). A carcinoma that arises from epithelial cells of the prostate gland. "Serum levels of CXCL2 and CXCL5 exhibited race-specific differences, while CCL23 showed both race- and cancer-specific differences supporting the potential contribution of systemic chemokines in differential outcomes among races in association with prostate cancer." (PMID 37698493, 2023). "Selected chemokines (CXCL2, CXCL5, and CCL23) serum level was validated in 211 serum samples from prostate cancer patients and healthy controls." (PMID 37698493, 2023). "In this study, we profiled the cytokine-chemokine serum levels associated with prostate cancer and demonstrated that serum chemokines CXCL2, CXCL5, and CCL23 are the most distinguished chemokines differentially expressed in men of AA and CA races." (PMID 37698493, 2023). "In summary, the elevated serum chemokines CXCL2 and CXCL5, in conjunction with a low level of CCL23, may contribute towards suppressed antitumor immunity and account for lethal prostate cancer in AA men." (PMID 37698493, 2023). "Lower levels of CCL23 in AA prostate cancer patient sera and tumor tissues and high CXCL2 and CXCL5 may contribute to aggressive prostate cancer, as often seen in AA men." (PMID 37698493, 2023). "In contrast, race-specific differences were observed for significantly higher serum levels of CXCL2 (p < 0.0001), CXCL5 (p = 0.016), and IL-6 (p = 0.004), and lower levels of CCL23 (p < 0.0001) and CCL27 (p = 0.016) in AA prostate cancer patients (n = 14) compared to CA (n = 14)." (PMID 37698493, 2023).
prostate tumors (1 paper, 2023). "To assess if CXCL5 and CCL23 are differentially expressed in prostate tumors, we performed immunohistochemistry (IHC) in archival prostate tumor tissues of AA and CA races." (PMID 37698493, 2023). "Differential expression of CXCL5 and CCL23 was analyzed using immunohistochemistry in a representative cohort of prostate tumor tissues of AA and CA races." (PMID 37698493, 2023). "Immunostaining for CXCL5 and CCL23 in a representative cohort of archival prostate tissues displayed significantly higher CXCL5 in prostate tumors than in adjacent benign tissues, while CCL23 was non-detectable in most of the analyzed tumor tissues." (PMID 37698493, 2023). "Similarly, no racial differences in CCL23 expression were observed in the analyzed 20 cases of prostate tumor tissues (10 each from AA and CA)." (PMID 37698493, 2023).
prostatitis (1 paper, 2025). An infectious or non-infectious inflammatory process affecting the prostate gland. "Reverse MR analysis suggests that prostatitis can reduce the levels of 3 inflammatory cytokines: chemokine (C-C motif) ligand 23 (CCL23), IL-5, and TNF-related activation-induced cytokine (TRANCE)." (PMID 40355178, 2025).
psoriatic arthritis (1 paper, 2020). Joint inflammation associated with psoriasis. "In psoriatic arthritis subjects, MPIF-1 (CCL23) was upregulated in the apremilast arm." (PMID 31953524, 2020).
thymoma (1 paper, 2024). A neoplasm arising from the epithelial cells of the thymus. "Patients with hyperplasia and thymoma differed in several proteins, including IL-18R1, TRAIL, CCL23, CX3CL1, CD8A, IL-8, TNF-β, and CCL11." (PMID 39165841, 2024).
urothelial bladder cancer (1 paper, 2023). "Plasma from muscle-invasive, urothelial bladder cancer patients displayed higher levels of MMP7 (p = 0.028) and CCL23 (p = 0.03) compared to NMIBC patients, whereas urine displayed higher levels of CD27 (p = 0.044) and CD40 (p = 0.04) in the NMIBC group by two-sided Wilcoxon rank-sum tests." (PMID 37391708, 2023).